STK17A (serine/threonine kinase 17a)
Description:
Acts as a positive regulator of apoptosis. Also acts as a regulator of cellular reactive oxygen species.
Synonyms: DRAK1
Tractability: Small molecule: a structure with a bound ligand is known; a high-quality ligand is known; it belongs to a druggable protein family. Antibody: its Gene Ontology location is reachable by antibodies, with high confidence. PROTAC: it is named in the literature on targeted protein degradation; ubiquitination databases record sites on it; a small molecule that binds it is known.
Target class: CAMK protein kinase group; Kinase; CAMK protein kinase DAPK family; Protein Kinase; Enzyme
Chemical probes: CK156 (high quality)
Gene: Protein-coding gene on chromosome 7 (43,582,758 to 43,650,713, forward strand). Ensembl gene ENSG00000164543.
Subcellular location: Nucleus
Subcellular location (Human Protein Atlas): Nuclear speckles; Plasma membrane
Gene Ontology:
Molecular function: ATP binding; protein serine/threonine kinase activity; protein kinase activity; protein serine kinase activity
Biological process: intracellular signal transduction; positive regulation of apoptotic process; positive regulation of fibroblast apoptotic process; protein phosphorylation; regulation of reactive oxygen species metabolic process
Cellular component: nuclear speck; nucleus
Genetic constraint (gnomAD): Loss-of-function variants: 22 observed, 35.01 expected, observed/expected ratio (o/e) 0.63, 90% interval 0.45 to 0.9. The upper end of that interval is the gene's LOEUF score, 0.9, which puts it in group 3 of 6, group 1 being the genes least tolerant of losing a copy. Missense variants: 437 observed, 434.33 expected, observed/expected ratio (o/e) 1.01, 90% interval 0.93 to 1.09. Synonymous variants: 177 observed, 153.85 expected, observed/expected ratio (o/e) 1.15, 90% interval 1.02 to 1.3.
Homologues: Orthologues: chimpanzee STK17A (99% identical), macaque STK17A (98% identical), dog STK17A (88% identical), pig STK17A (88% identical), rabbit STK17A (87% identical), guinea pig STK17A (75% identical), tropical clawed frog stk17a (65% identical), zebrafish stk17a (63% identical), Drosophila melanogaster Drak (41% identical). Paralogues in human: STK17B (49% identical).
Diseases named in the same sentence as STK17A in open-access papers:
STK17A is named in the same sentence as 27 diseases in open-access papers, as found by Europe PMC text mining. Sharing a sentence is not in itself a finding about the gene and the disease. The quoted sentences say what the papers report.
glioblastoma (5 papers, 2013 to 2023). The most malignant astrocytic tumor (WHO grade IV). "On the other hand, up-regulated STK17A in glioblastomas has been reported, where it was associated with tumor grade and patient survival." (PMID 26305096, 2015). "Interestingly overexpression of STK17A has been reported in other cancers like glioblastoma where it has been implicated to correlate to poor prognosis in those patients." (PMID 24403257, 2013). "In this study we have uncovered an additional, unanticipated role for STK17A as a candidate promoter of cell proliferation and survival in glioblastoma (GBM)." (PMID 24312360, 2013).
colorectal cancer (3 papers, 2013 to 2023). A primary or metastatic malignant neoplasm that affects the colon or rectum. "Since STK17A is known as a positive regulator of the apoptotic pathway and its expression level in colorectal carcinomas is enhanced in lesions with lymph node metastasis, the apoptotic process could be involved in the node metastasis of carcinomas, including CUP." (PMID 23671674, 2013). "In the context of colon adenocarcinoma and colorectal cancer (CRC), STK17A downregulation has been observed." (PMID 37627077, 2023).
head and neck squamous cell carcinoma (3 papers, 2015 to 2022). A squamous cell carcinoma that arises from any of the following anatomic sites: lip and oral cavity, nasal cavity, paranasal sinuses, pharynx, larynx, and salivary glands. "Moreover, STK17A has been found to be overexpressed in human head and neck squamous cell carcinoma by inhibiting the tumor suppressive activity of transforming growth factor (TGF)-beta signaling." (PMID 26305096, 2015).
testicular cancer (3 papers, 2013 to 2019). A primary or metastatic malignant neoplasm that affects the testis. "Our current and previous work suggests that STK17A may have context dependent activities since STK17A was associated with cisplatin sensitivity in testicular cancer cells which express very low levels of basal STK17A that is highly induced upon genotoxic stress." (PMID 24312360, 2013).
bipolar disorder (1 paper, 2011). A disorder of the brain that causes unusual shifts in mood, energy, activity levels and the ability to carry out day-to-day tasks. "These genes included SBNO2, CEACAM5, AKAP1, UBC, ACTB, UBB, and FOS for schizophrenia; SEC24C, PGLYRP1, ARHGAP4, RPL22, SLC6A11, and SYK for bipolar disorder; and SRRT, PARK2, LILRA4, STK17A, IGFBP2, and NF1 for major depression." (PMID 22373040, 2011).
breast carcinoma (1 paper, 2018). "Sixteen understudied kinases showed strong variance between TNBC and HER2/luminal breast cancer, with higher-ranked understudied kinases being DAPK3, ADCK1, MRCKA (CDC42BPA), STK17A, DMPK and VRK2." (PMID 29643987, 2018).
cataract (1 paper, 2024). Partial or complete opacity of the crystalline lens of one or both eyes that decreases visual acuity and eventually results in blindness. "Follow-up analysis of the shared loci implicates candidate genes QKI, STK17A, TYR, NSF, and TCF4 likely contribute to the pathophysiology of cataracts and hearing difficulties." (PMID 38632618, 2024).
glioma (1 paper, 2013). A benign or malignant brain and spinal cord tumor that arises from glial cells (astrocytes, oligodendrocytes, ependymal cells). "The association of STK17A expression with patient survival suggests that STK17A is a potentially important new kinase target in glioma." (PMID 24312360, 2013). "Further, high levels of STK17A were associated with poor survival in patients with glioma indicating that STK17A may have clinical relevance as a therapeutic target in these neoplasms." (PMID 24312360, 2013). "Increased expression of STK17A was associated with a highly significant decrease in overall patient survival when assessed by the Kaplan-Meier log-rank test in a combined cohort of all patients with glioma from the TCGA database." (PMID 24312360, 2013). "In conclusion, this study indicates that STK17A is overexpressed in gliomas in a manner that corresponds with increasing tumor grade and malignancy." (PMID 24312360, 2013). "Further, the Cancer Cell Line Encyclopedia (CCLE) database demonstrated that of 1062 cell lines representing 37 distinct cancer types, glioma cell lines express the highest levels of STK17A." (PMID 24312360, 2013). "Unexpectedly, the most significant alteration found was prominent overexpression of STK17A in human glioma." (PMID 24312360, 2013). "Unexpectedly, it was found that STK17A is highly overexpressed in a grade-dependent manner in gliomas compared to normal brain and other cancer cell types with the highest level of expression in GBM." (PMID 24312360, 2013). "Together the data suggests that STK17A is an independent predictor of survival in glioma patients, but since STK17A expression is highly grade-dependent, grade is likely a partially confounding factor." (PMID 24312360, 2013). "In summary, we have uncovered an unrecognized role for STK17A in glioma biology." (PMID 24312360, 2013). "Here we have identified STK17A as a novel candidate kinase target in gliomas." (PMID 24312360, 2013). "Here we provide evidence for an unanticipated oncogenic role for STK17A in glioma." (PMID 24312360, 2013). "STK17A was highly expressed in a grade-dependent manner in gliomas when compared to normal brain." (PMID 24312360, 2013). "Importantly, STK17A knockdown also sensitized GBM cells to genotoxic stress and STK17A overexpression was associated with a significant survival disadvantage among patients with glioma." (PMID 24312360, 2013). "In summary, we demonstrate that STK17A provides a proliferative and survival advantage to GBM cells and is a potential target to be exploited therapeutically in patients with glioma." (PMID 24312360, 2013).
leukemia (1 paper, 2023). A malignant (clonal) hematologic disorder, involving hematopoietic stem cells and characterized by the presence of primitive or atypical myeloid or lymphoid cells in the bone marrow and the blood. "The DNAm levels at three individual CG dinucleotides (CpG sites) in the genes MYO1D, STK17A, and SP140 correlated with CD34+ cell numbers in mobilized peripheral blood and with blast counts in leukemia." (PMID 37370186, 2023).
ovarian carcinoma (1 paper, 2020). A malignant neoplasm originating from the surface ovarian epithelium. "Additionally, in ovarian cancer cells, STK17A was found to be characteristic for a drug-resistance phenotype." (PMID 32455542, 2020).
cancer (13 papers, 2013 to 2026). A tumor composed of atypical neoplastic, often pleomorphic cells that invade other tissues. "Nonetheless, challenges of selectivity and functional validation remain, emphasizing the need for continued medicinal chemistry efforts to unlock the full potential of STK17A as a therapeutic target across cancer, autoimmune, and neurodegenerative diseases." (PMID 42094611, 2026). "In this review, we summarize current knowledge on STK17A, including its structure, evolution, expression patterns, molecular interactions, and roles in cancer as well as in autoimmune, cardiovascular, infectious, and neurological disorders." (PMID 42094611, 2026). "Although the involvement of STK17A in cancer is well-documented, recent research has also highlighted its importance in non-cancerous diseases." (PMID 38402348, 2024). "This decrease in STK17A levels is responsible for the morphological changes observed in adenocarcinoma and CRC, leading to an elevated rate of invasion by cancer cells." (PMID 37627077, 2023). "Targeting STK17A may lead to the development of new therapies for GBM and other cancers and may provide a new strategy to sensitize cancers to existing therapies." (PMID 24312360, 2013).
tumor (8 papers, 2013 to 2023). "The deregulation or downregulation of STK17A is associated with tumor development, progression, and resistance to therapy." (PMID 37627077, 2023). "We also confirmed that STK17A mRNA levels were increased in GBM tumor tissue compared to STK17A levels in normal brain." (PMID 24312360, 2013). "Increased nuclear expression of RB1 [RB1(N)↑], CDH3(C)↑-STK17A(N)↑ and FLNA(C)↑-KRAS(C)↑were associated with survival, but not independent of tumor stage, where C and N denote cytoplasm and nucleus, respectively." (PMID 33936170, 2021). "There was no quantification difference between tumor and non-malignant tissues for STK17A gene, but difference was detected for the SRCC-specific isoform." (PMID 32732980, 2020).
STK17A also shares sentences with these, for which no sentence is quoted: cervical cancer (5 papers); head and neck cancer (2); adenocarcinoma (1); colon adenocarcinoma (1); diabetes (1); digestive system cancer (1); embryonal carcinoma (1); fibrosarcoma (1); major depression (1); neurodegenerative disease (1); neurological disorders (1); osteosarcoma (1); papillary renal cell carcinoma (1); prostate carcinoma (1); schizophrenia (1).